IRS1 (insulin receptor substrate 1)
Diseases named in the same sentence as IRS1 in open-access papers (continued):
Sharing a sentence is not in itself a finding about the gene and the disease.
Insulin resistance (continued). "HCV-NS5A is known to promote insulin resistance through IRS-1 serine phosphorylation contributing to gluconeogenesis." (PMID 35055105, 2022). "Taken together, HM-chromanone improved palmitate-induced insulin resistance by decreasing insulin resistance inducers and regulating phosphorylation of IRS-1 residues in L6 skeletal muscle cells." (PMID 36145191, 2022). "IRS-1 and GLUT4 expression in AT is typically decreased in obesity and associated with insulin resistance." (PMID 36432612, 2022). "In adipose, ER stress triggers activation of c-Jun N-terminal kinase (JNK) through activated inositol requiring 1 alpha (IRE1 α), thereby inhibiting serine phosphorylation of IRS1, and resulting in insulin resistance." (PMID 35990905, 2022). "Because the IRS1/Akt signaling transduction pathway plays a critical role in insulin resistance, we further elucidated the effect of ICS II on the IRS1/Akt signaling transduction pathway." (PMID 36139776, 2022). "BCAA-mediated insulin resistance occurs because it inhibits the phosphorylation of the insulin receptor (IRS-1)." (PMID 36542005, 2022). "In obese rats, insulin resistance isrelated to alterations in the expression of insulin receptor substrate-1 (IRS-1) andreduction in the expression of GLUT4, PI3K, and Akt." (PMID 35857997, 2022). "On the other hand, ROCK1/AMPK/SREBP1c and ROCK/IRS1 pathways have been found involved in lipotoxicity and insulin resistance on HFD." (PMID 35769086, 2022). "Ginsenoside promotes the expression of IRS-1 in the insulin signaling pathway and played a crucial role in alleviating inflammation and insulin resistance in obesity." (PMID 35069931, 2022). "TNF-α phosphorylates Serine307 of IRS-1(insulin receptor substrate 1) by activating downstream c-Jun NH2-terminal kinase (JNK), impairing glucose uptake and causing insulin resistance in adipose tissue." (PMID 36496995, 2022). "GM3 inhibits insulin receptor signaling to IRS-1, therefore creating a state of insulin resistance by preventing downstream signaling events." (PMID 36499769, 2022). "High glucose, FA, hormones, and inflammation can induce insulin resistance in the skeletal muscle by inhibiting IRS1." (PMID 35955653, 2022). "Serine phosphorylation of IRS1 increases with insulin resistance, and serine hyperphosphorylation of IRS1 is thought to be a negative regulator of insulin signal transduction in general." (PMID 36589630, 2022). "IRS1 plays critical roles not only in the transduction of insulin signals but also in the development of insulin resistance." (PMID 35790738, 2022). "TNF induced insulin resistance in adipocytes by inhibiting insulin-induced IRS1 tyrosine phosphorylation and insulin-induced glucose uptake and played a role in angiogenesis by inducing VEGF production synergistically with IL-1B and IL-6." (PMID 34306139, 2021). "Activation of TNF-α triggers insulin resistance by increasing uptake of glucose in visceral and subcutaneous adipocytes and through phosphorylation of serine 307 in IRS-1." (PMID 33986669, 2021). "Like the IKKβ/NF-κB pathway, JNK pathway also promotes insulin resistance by promoting proinflammatory and serine phosphorylation of IRS-1." (PMID 33917607, 2021). "Increased serine phosphorylation of insulin receptor substrate 1 (IRS1) proteins reveals a signature of insulin resistance." (PMID 33946318, 2021). "IRS-1- and IRS-2-deficient mice not only exhibited insulin resistance but also diminished eNOS activity." (PMID 34440804, 2021). "Fbxo40, a muscle-specific E3 ubiquitin ligase targeting the IRS1 for degradation, is activated by Stat3 and contributes to muscular insulin resistance." (PMID 34943061, 2021). "We then evaluated the insulin resistance in the mouse hippocampus by measuring the degree of phosphorylation of IRS-1, AKT, and GSK-3β using western blot analysis." (PMID 33859286, 2021).
Insulin resistance (continued). "This bioactive molecule can lead to the activation of PI3K/Akt/mTOR insulin receptor substrate 1 (through IRS-1) phosphorylation, promoting insulin signalling pathway activation and thereby reducing insulin resistance." (PMID 34579001, 2021). "The IRS-1/PI3K/Akt/Glut4 signaling pathway is a classical insulin signaling pathway that plays an influential role in alleviating diabetes-induced insulin resistance." (PMID 34691353, 2021). "TNF-α has been known to stimulate serine phosphorylation of insulin receptor substrate 1, resulting in insulin resistance." (PMID 33669954, 2021). "mTOR-S6K1-mediated phosphorylation of IRS-1, and degradation of IRS-1 and InsR via the proteasomal or lysosomal pathway, respectively, were implicated in the mechanism of insulin-induced insulin resistance in these NPY/AgRP-expressing cells." (PMID 34831343, 2021). "In this present study, WVBF treatment increases gene expressions of Irs1 significantly, which alleviate insulin resistance in diabetic rats." (PMID 34899339, 2021). "Ex-4 was reported to improve neuronal insulin resistance both in vivo and in vitro experiments by preventing pathological phosphorylation of IRS-1, which interferes with its function to activate the downstream signaling cascade of insulin." (PMID 33616807, 2021). "Another important functional aspect of TNF-α is the ability to contribute to insulin resistance by inhibiting tyrosine phosphorylation of insulin receptor substrate-1 (IRS-1)." (PMID 34211985, 2021). "Ang II impairs Akt and mTORC1 signalling by inhibiting the IGF1 signalling axis while simultaneously promoting atrogene transcription, alongside inducing ROS production as well as insulin resistance via inhibition of IRS1 via protein kinase C (PKC) activation." (PMID 33225593, 2021). "High concentrations of BCAAs activate the mTORC1/S6K1 kinase pathway, resulting in insulin resistance through the phosphorylation of insulin receptor substrate 1 (IRS-1), leading to blocked insulin signaling." (PMID 34684308, 2021). "FGF19 treatment restored PA‐ and HFD‐induced hyperglycaemia, impaired glucose tolerance and insulin resistance (IRS‐1, GLUT‐4) and mitigated the PA‐ and HFD‐induced decrease in FNDC‐5/irisin expression." (PMID 33751819, 2021). "In this regard, in knock-in mice with a mutation in which the authors replaced Ser 307 with Ala 307 in IRS1 resulted in increased insulin resistance." (PMID 34069890, 2021). "Insulin receptor substrate 1 (IRS1), the key kinase for glucose uptake and the target of insulin resistance, is a signaling factor downstream of the insulin receptor." (PMID 34071638, 2021). "Muscle mitsugumin 53 (MG53), a newly identified muscle-specific protein, is one pivotal element of insulin resistance in type 2 diabetes by participating in the insulin degradation process through insulin receptor substrate-1 (IRS-1) and the p-AKT pathway." (PMID 34163437, 2021). "For example, insulin resistance has been shown to promote hepatic steatosis via insulin receptor substrate-1 (IRS1) activation of sterol regulatory element-binding protein-1c (SREBP1c), the major regulator of hepatic fatty acid synthesis." (PMID 34298687, 2021). "It has been reported that “GDM patients had decreased levels of IRS-1” indicating that in DGM patients there is increased levels of insulin resistance." (PMID 34055923, 2021). "TNF-α was reported to be high in the adipose tissue of obese individuals, and its level was correlated positively with insulin resistance as it interferes with the insulin signalling transduction via serine-phosphorylation of IRS-1." (PMID 33557218, 2021). "Chronic insulin stimulation degrades insulin receptor substrate 1 and 2 (IRS1 and IRS2) protein and causes insulin resistance in vitro." (PMID 33547878, 2021). "Fascinatingly, patients with insulin-resistance show abnormally phosphorylated IRS1, which hinders the IR-dependent signaling cascade." (PMID 33058005, 2021).
Insulin resistance (continued). "TNFα-associated hepatic insulin resistance is probably mediated by TNF receptors by activating a kinase (c-Jun-NH2-terminal kinase), which in turn catalyzes serine phosphorylation of insulin receptor substrate 1 (IRS-1)." (PMID 34574008, 2021). "Danhong injection treatment ameliorated HFD-induced AS and insulin resistance by activating the PI3K/AKT insulin pathway induced by insulin receptor substance-1 (IRS-1)." (PMID 34873408, 2021). "Neuroinflammation has been linked with neuronal insulin resistance, due to the TNFα-JNK pathway-mediated IRS1 inhibition." (PMID 34069890, 2021). "Th evidence indicates that IKK and JNK are plausible mechanistic links between TNF-α and insulin resistance through the phosphorylation of IRS1 at the inhibitory moiety." (PMID 34073455, 2021). "Inhibitors of DPP-4 improve neuronal insulin resistance by restoring insulin-induced phosphorylation of neuronal IR, IRS1 phosphorylation, and AKT/PKB-Ser phosphorylation, resulting in the brain mitochondrial dysfunction." (PMID 34489627, 2021). "High saturated fatty acid levels, which can suppress normal IRS1 tyrosine phosphorylation and induce insulin resistance in skeletal muscle, show a correlation with skeletal muscle insulin activity." (PMID 34489627, 2021). "SOCS-1 and SOCS-3 induced insulin resistance by inhibiting phosphorylation of insulin receptors IRS-1 and IRS-2 and downstream signaling in mice liver." (PMID 33924165, 2021). "Activated S6K phosphorylates IRS-1 proteins and results in insulin resistance in the cells during diabetes." (PMID 35178356, 2021). "In adipocytes, activated JNK1 blocks the activity of IRS-1 (insulin receptor substrate-1), leading to reduced insulin signaling and the development of insulin resistance." (PMID 34371968, 2021). "In the liver, this high activation promotes hepatic insulin resistance through the degradation of IRS1, contributing to the dysregulation of glucose and lipid homeostasis." (PMID 34069890, 2021). "Brain insulin resistance has been demonstrated in early AD through decreased IR, IRS-1, and PI3K signaling in mildly symptomatic as well as severely symptomatic patients." (PMID 33920138, 2021). "In 2013, it was reported that MG53 is upregulated in models of insulin resistance and that it modifies insulin signaling by targeting the degradation of the insulin receptor β-subunit and of IRS1 by its ubiquitin E3 ligase activity." (PMID 34440850, 2021). "ER stress is believed to cause insulin resistance via the activation of JNK, which leads to the inhibition of IRS-1 by phosphorylating the serine residue." (PMID 33995826, 2021). "In particular, TNF-α aggravates insulin resistance via activation of c-Jun kinase, which inhibits the phosphorylation of insulin receptor substrate-1 and hence blocks insulin signaling, resulting in exacerbation of the inflammatory response." (PMID 34366841, 2021). "Phosphorylation of IRS1 at its serine residues, specifically on Ser307, Ser612, and Ser632, serves as a core element in the development of insulin resistance." (PMID 34445300, 2021). "We did not select SNPs in known coding regions for the exposures, for example, the IRS-1 gene for insulin resistance." (PMID 33711016, 2021). "Together with the observation in metabolic-imbalanced neurons, our findings reveal that exendin-4 ameliorated insulin resistance through the IRS-1/AKT/GSK-3β pathway in metabolic imbalance in the HFD mouse brain." (PMID 33859286, 2021). "During inflammation, activation of mTORC1 and its effector S6K leads to phosphorylation of IRS-1 and insulin resistance, an important phenomenon in the pathophysiology of diabetes." (PMID 35178356, 2021). "β-Sitosterol attenuates insulin resistance and high fat diet-induced detrimental changes via mediating IRS-1/AKT signaling for the management of T2DM." (PMID 34349832, 2021).
Insulin resistance (continued). "And our results from western blotting suggested that rh-aFGF135 regulate insulin resistance partially by activating phosphorylation of IRS-1 (human Ser 307) in HepG2 cells." (PMID 33681196, 2021). "One study conducted in mice deficient in S6K1 demonstrated that mice were protected against insulin resistance under high-fat diet (HFD) conditions, which was apparent in the loss of negative regulation from S6K1 through its serine phosphorylation of IRS1." (PMID 34445300, 2021). "Neuronal insulin resistance instigated by hyperphosphorylation of IRS-1 at the Ser636/312/307 residues and downregulation of p-IRS-1Tyr 632 has been associated with AD pathology and reported in Aβ and APP/PS1 mouse AD models as well as HFD and Adipo−/− mice." (PMID 33849621, 2021). "Some research, particularly in animal models of insulin resistance, have shown that brain insulin signaling plays a role in neuropathology including as relevant to cerebrovascular disease, such as IRS1/AKT in hypoxic brain injury." (PMID 33858515, 2021). "In neuronal cultures and mice expressing mutant A53T α-Synuclein, mTORC1 signaling is overactivated, also resulting in insulin resistance (via IRS-1, S636 phosphorylation)." (PMID 34215308, 2021). "Because S6K1 can catalyze the inhibitory serine phosphorylation of insulin receptor substrate‐1 (IRS‐1) and thereby induce insulin resistance, we examined the phosphorylation of this kinase." (PMID 33400857, 2021). "Meanwhile, some studies indicated that the HCV core protein is involved in the induction of insulin resistance through insulin receptor substrate-1 pathway signaling." (PMID 34311776, 2021). "The function of TNF-α in insulin resistance is realized by serine phosphorylation of insulin receptor substrate-1 and downregulation of insulin-sensitive glucose transport protein." (PMID 34637688, 2021). "IRS1 also integrates the feedback signals and communicates with other signaling pathways, which triggers the onset of insulin resistance." (PMID 34899339, 2021). "Insulin resistance stimulates serine/threonine kinases that phosphorylate IRS-1, thereby inhibiting its normal functions." (PMID 33995826, 2021). "One of the most obvious mechanisms of insulin resistance generation is through the modulation of IRS1 phosphorylation status, suggested using in vitro approaches." (PMID 34069890, 2021). "It is reported that the mice knockout for SCF Fbxo40 shown elevated levels of IRS1 of the insulin signaling pathway and play a vital role in insulin resistance." (PMID 33669862, 2021). "These stress kinases not only hamper the IRS1 function but promote insulin resistance through upregulation of the expression of genes involved in the activation of inflammation and nuclear factor kappa B (NF-κB), thus further intensifying the problem." (PMID 34445300, 2021). "This analysis confirmed that the liver of Hsp10 KD mice exhibited a molecular signature of insulin resistance with 40% increased S1101 and S632 phosphorylation of IRS1 and increased SOCS3 levels." (PMID 33946318, 2021). "JNK has been shown to promote insulin resistance by inhibiting the signal through insulin receptor/IRS-1 axis." (PMID 33435282, 2021). "Insulin resistance is mediated when the expression of p85α monomer is enhanced as it competes with p85-p110 heterodimer and sequesters IRS1 and recruits inhibitory proteins responsible for PIP3 degradation." (PMID 34445300, 2021). "We then examined the phosphorylation status of insulin receptor substrate 1 (IRS-1) because serine/threonine phosphorylation of IRS-1 is closely related to insulin resistance." (PMID 34684470, 2021). "Hsp10 KD cells exhibit insulin resistance under basal conditions, as evidenced by a 48% increase of IRS1 S1101 phosphorylation, and also showed acute insulin resistance, compared to control." (PMID 33946318, 2021).
Insulin resistance (continued). "DHM reversed the metabolic syndrome by upregulating insulin receptor substrate-1 (IRS-1) (y612) tyrosine phosphorylation and improving insulin resistance in obese mice." (PMID 35115939, 2021). "S6K1 negatively regulates the PI3K/mTOR pathway by phosphorylating serine residues in insulin receptor substrate 1 (IRS1), leading to insulin resistance." (PMID 34276336, 2021). "Exhibited antioxidant effect, improved hepatic insulin resistance by modulating IRS1/PI3K/AKT2 pathways." (PMID 34299610, 2021). "As a major signaling adapter of the insulin/IGF-1 signaling pathway, IRS-1 stimulates a variety of downstream pathways to participate in the regulation of insulin resistance and cell differentiation." (PMID 34295306, 2021). "It is reported that ROS have been playing a significant function in FFA-induced insulin resistance by insulin receptor substrate-1 phosphorylation in serine residue and by inhibiting downstream insulin signaling." (PMID 34201185, 2021). "The insulin receptor substrate-1 (IRS1) is a well-known regulator of insulin resistance both in vitro and in vivo." (PMID 34071638, 2021). "TNF-α induces insulin receptor substrate 1 (IRS-1) serine phosphorylation, downregulating insulin action and linking inflammation to insulin resistance in pregnancies." (PMID 34769262, 2021). "The main mechanism by which TNF-α induces insulin resistance is by triggering post-receptor serine phosphorylation of insulin receptor substrate-1 (IRS-1) thereby interfering with the insulin signalling pathway." (PMID 33800490, 2021). "Compared with TNFα treatment, DHM activated IRS-1 indicating that DHM ameliorated the TNFα-induced insulin resistance." (PMID 34650665, 2021). "β-sitosterol attenuates insulin resistance by reducing insulin receptor substrate-1 (IRS-1) serine phosphorylation and activating downstream signaling molecules in rats." (PMID 34827970, 2021). "As downstream effector of ASK1, JNK1 directly facilitated obesity‐related insulin resistance and ectopic hepatic lipid accumulation by promoting serine phosphorylation of IRS1 and inhibiting of Akt signalling in hepatocytes." (PMID 34734480, 2021). "Tau loss of function as a consequence of hyperphosphorylation and NFTs formation was recently suggested to be involved in brain insulin resistance via insulin receptor substrate 1 (IRS-1) and phosphatase and tensin homolog (PTEN) alterations." (PMID 33911072, 2021). "Previously, our group showed that PP4 formed a complex with IRS-1 and participated in inflammatory-related insulin resistance." (PMID 34221233, 2021). "Both cell types showed significantly reduced phosphorylation of IRS-1 under PA-induced insulin resistance conditions." (PMID 33435277, 2021). "Like TNF-α, IL-6 also promotes insulin resistance by attenuating the expression of IRS-1 and GLUT-4 and deregulating fatty acid metabolism in adipocytes." (PMID 33917607, 2021). "We previously identified that hepatic zonation of Irs1 plays a crucial role in selective insulin resistance." (PMID 33923817, 2021). "In contrast, CYC31 reversed the palmitate-induced insulin resistance by increasing the phosphorylation level of IR, IRS-1, and Akt." (PMID 32438641, 2020). "Studies have shown that IL-1 can activate the skeletal muscle IKKβ/NF-κB pathway, reduce IRS-1 activity, and promote skeletal muscle insulin resistance." (PMID 32082422, 2020). "What is more, it was demonstrated that the incubation of C2C12 myotubes with 1,25(OH)2D3 ameliorated lipid-induced insulin resistance by increased tyrosine phosphorylation of IRS-1 and serine phosphorylation of AKT." (PMID 32932777, 2020). "Its expression is increased in human obesity and strongly associated with insulin resistance by downregulating GLUT4 expression and by decreasing phosphorylation of IRS1." (PMID 32604889, 2020).